RNU6-525P (RNA, U6 small nuclear 525, pseudogene)
Gene: Small nuclear RNA gene on chromosome 5 (180,444,509 to 180,444,612, forward strand). Ensembl gene ENSG00000200555.
Homologues: Orthologues: chimpanzee U6 (100% identical), macaque U6 (96% identical), dog U6 (85% identical), pig U6 (85% identical), dog U6 (84% identical), mouse Gm25672 (83% identical), rabbit U6 (80% identical), guinea pig U6 (73% identical), guinea pig U6 (65% identical). Paralogues in human: RNU6-140P (87% identical), RNU6-403P (85% identical), RNU6-854P (85% identical), RNU6-1075P (84% identical), RNU6-1124P (84% identical), RNU6-1251P (84% identical), RNU6-246P (84% identical), RNU6-29P (84% identical), RNU6-338P (84% identical), RNU6-536P (84% identical), RNU6-1099P (83% identical), RNU6-1309P (83% identical), and 1284 more.